UCA1 (urothelial cancer associated 1)
Diseases named in the same sentence as UCA1 in open-access papers (continued):
Sharing a sentence is not in itself a finding about the gene and the disease.
tumor (continued). "Here it was suggested that homozygote CC of rs12982687 might prevent UCA1 expression from being suppressed by miR-873-5p, owing to which the anti-tumor role of miR-873-5p was hindered." (PMID 32143722, 2020). "Especially, UCA1 plays oncogenic roles in tumor growth and metastasis." (PMID 31040354, 2019). "Knockout of UCA1 significantly inhibit tumor growth in mice." (PMID 31272462, 2019). "Our study connects two hot research areas of tumor, namely, non-coding RNA and FA metabolism together and elucidates a new molecular mechanism underlying the PA induced GC metastasis via FABP5/SP1/UCA1 signaling which contributes to efficient prevention and therapeutic strategies for GC." (PMID 30948929, 2019). "As an oncogenic lncRNA, UCA1 is upregulated and exerts a tumor-promoting effect in CRC." (PMID 31744051, 2019). "CCAT1 and UCA1 showed upregulation in tumor samples compared to normal tissues." (PMID 31694571, 2019). "Besides, the cellular levels of UCA1 in GC tumor tissues were significantly higher than that in normal tissues." (PMID 30948929, 2019). "PTP1B up-regulation by UCA1 improved cell proliferation, and also promoted tumor cells growth." (PMID 31695578, 2019). "We noticed that CLOCK expression was suppressed by LV-sh-UCA1 in tumor tissues (p < 0.01)." (PMID 31798345, 2019). "From a functional perspective, UCA1 impairs tumor suppressive effects of miR-204 in PCa cells." (PMID 30940776, 2019). "LncRNA urothelial cancer-associated 1 (UCA1) is overexpressed in TSCC tumor tissues compared to neighboring non-tumor tissues." (PMID 31336999, 2019). "It has been postulated that a signaling pathway may be involved in the formation of a regulatory loop between lncRNA UCA1 and miR-145 via a reciprocal repression process required for tumor cell-specific activities (e.g., migration and/or invasion)." (PMID 31293964, 2019). "In addition, we also found miR-214 and -193 have the potential to be ‘sponged’ by UCA1, and both were reported function as tumor suppressors." (PMID 31272462, 2019). "The results demonstrated that tumor growth was inhibited in vivo after UCA1 was deleted." (PMID 31133028, 2019). "It is reported that UCA1 was involved in tumor cell glycolysis." (PMID 31040354, 2019). "In addition, qRT-PCR analysis of relevant gene expression levels in the isolated tumor tissues showed that the expression of UCA1, β-catenin and cyclin D1 was up-regulated, while the expression of axin was down-regulated from the UCA1 group." (PMID 31596734, 2019). "Furthermore, it has been reported that lncRNA UCA1 suppresses the tumor suppressor miR-145 for tumor cell invasion/migration through the expression of miR-145 target proteins such as ROCK1 in glioma cancer cells." (PMID 31293964, 2019). "Knockdown of UCA1 inhibits tumor growth in vivo, suggesting that UCA1 may provide a lncRNA-oriented diagnostic and therapeutic strategy for OSCC." (PMID 29416703, 2018). "Examples include the lncRNAs H19, HOTAIR (HOX transcript antisense RNA), and UCA1 (urothelial cancer associated 1, non-protein coding), which silence tumor suppressor genes." (PMID 29983835, 2018). "Moreover, higher levels of UCA1 were also detected in serum of HCC patients and are associated with higher grade, larger tumor size, higher TNM stage, and vascular invasion, acting as an independent unfavorable prognostic factor for HCC." (PMID 29495592, 2018). "Since UCA1 expression in CRC may depend on primary tumor localization and molecular subtypes, its prognostic value may be restrictive to different CRC subclasses." (PMID 30441811, 2018). "For instance, UCA1 levels in HCC tissues and in serum were associated with high tumor grade, large tumor size, positive vascular invasion, and advanced TNM stage and may be an independent prognostic indicator." (PMID 29495592, 2018). "We showed that knockdown of UCA1 inhibited tumor growth in vivo." (PMID 29516678, 2018). "We demonstrated that knockdown of UCA1 inhibits tumor growth in vivo." (PMID 29516678, 2018).
tumor (continued). "BMP9 remarkably increased the growth of transplanted tumor in a UCA1 dependent way." (PMID 29642505, 2018). "Increased UCA1 level promotes cell migration and invasion, and inhibition of UCA1 may be a candidate to suppress cell migration and invasion in tumor progression." (PMID 30464170, 2018). "A number of noncoding RNAs such as urothelial cancer associated 1 (UCA1), MALAT1, H19, and plasmacytoma variant translocation (PVT1) have been implicated in the promotion of metastasis of tumour cells, but evidence for a more direct role of these RNAs in this process is still lacking." (PMID 30296263, 2018). "In addition, we performed qRT-PCR in mouse tumor tissues and confirmed the significance of UCA1 overexpression in LV-UCA1 group." (PMID 28624787, 2017). "Similar expression patterns across these tumour samples became evident for UCA1 and MALAT1, suggesting that patients with low expression of these lncRNAs might also belong to the BASQ subtype." (PMID 28430799, 2017). "For example, MALAT1 or UCA1 could play important roles in facilitating genome-wide occupancy of EZH2 onto chromatin in tumor cells." (PMID 29050269, 2017). "The nude mouse model of xenograft further validated that depletion of UCA1 could enhance CDDP‐mediated repression on OSCC tumor growth." (PMID 29125238, 2017). "In vitro studies results indicated that depletion of UCA1 might have anti‐tumor effect and can enhance CDDP sensibility in CDDP‐resistant OSCC cells." (PMID 29125238, 2017). "Mechanistically, we found that UCA1, one of the most important lncRNAs in malignancies of the urinary system, may be a potential mediator contributing to the tumor suppressor function of ART." (PMID 28209917, 2017). "In vivo analysis further validated that depletion of UCA1 could boost CDDP‐mediated repression on tumor growth." (PMID 29125238, 2017). "The results indicated that UCA1 transcription is enhanced in both CCA tissue samples and cell lines, and this overexpression is associated with tumor stage (P = 0.007), lymph node invasion (P = 0.027), TNM stage (P = 0.004) and postoperative recurrence (P = 0.033) of CCA patients." (PMID 29221199, 2017). "Moreover, the average tumor weight at the end of the experiment was significantly lower in the UCA1 silenced group (0.46 ± 0.12 g) compared to the blank group (0.84 ± 0.17g) and the empty vector group (0.88 ± 0.35g), (P < 0.05)." (PMID 29212166, 2017). "UCA1 expression in tumor tissues and cells was tested by qRT‐PCR." (PMID 29125238, 2017). "Moreover, we also demonstrated that downregulation of miR‐184 alleviated si‐UCA1‐mediated CDDP susceptibility and tumor inhibition effect." (PMID 29125238, 2017). "LncRNA UCA1 was found to be overexpressed in TSCCs and to promote tumour metastasis." (PMID 28112249, 2017). "miR-1 plays a tumor suppressive role by binding and inhibiting UCA1 in bladder cancer." (PMID 27046651, 2016). "UCA1 overexpression was often accompanied by tumor metastasis, suggesting that this lncRNA could be clinically useful as a diagnostic and prognostic indicator for ESCC patients." (PMID 27686732, 2016). "Obviously, simultaneous knockdown of UCA1 and HBx further inhibited tumours formation." (PMID 27009634, 2016). "To investigate whether UCA1 expression is correlated with HBx levels in HCC tissues, we examined the mRNA levels of HBx and UCA1 in 60 paired tumour and non-tumour specimens by real-time PCR." (PMID 27009634, 2016). "Premature senescence resulting from overexpression of UCA1 in HFFs reveals that this lncRNA is a novel regulator of cell proliferation and may function as a tumor suppressor in some contexts." (PMID 24876127, 2014). "Finally, the overexpression of UCA1 promoted tumor progression in HR+ BC tissues." (PMID 38534790, 2024). "Therefore, the UCA1/miR-485-5p/MMP14 axis may provide a potential strategy for targeting tumor metastasis-related therapies." (PMID 38725621, 2024). "Moreover, silencing of UCA1 led to significant tumor suppression in vivo." (PMID 38534790, 2024).
tumor (continued). "Finally, UCA1 was evaluated as overexpressed in both tumor tissues and CC plasma exosomes." (PMID 38534790, 2024). "UCA1 overexpression was shown to downregulate the SWI/SNF-related, matrix-associated, actin-dependent regulator of chromatin, subfamily d, member 3 (SMARCD3) via ubiquitin-mediated proteolysis in HeLa and ME180 cells, resulting in the progression of tumor growth." (PMID 38534790, 2024). "To determine the clinical significance of LUCAT1, UCA1, and MIR31HG in HNC, we evaluated the associations of molecular expression with clinical presentations to assess their predictive power in diagnosis and prognosis using TCGA-HNSC data of the 43 HNC patients with paired normal and tumor samples." (PMID 36980216, 2023). "Furthermore, the UCA1 expression level is correlated with the tumor size." (PMID 36699052, 2022). "In addition, UCA1 could promote tumor growth and angiogenesis through the UCA1/miR-96-5p/AMOTL2, ERK1, ERK2 axis." (PMID 34760707, 2021). "However, the relationship between UCA1 expression and tumor stage is the opposite (P = .029)." (PMID 33832120, 2021). "Moreover, the UCA1 expression level was positively related to tumor stages." (PMID 34733326, 2021). "Moreover, the UCA1 expression level was positively correlated to tumor stages." (PMID 34733326, 2021). "Thus, knockdown of UCA1 inhibited tumor growth by regulating miR‐590‐3p expression in vivo." (PMID 29516678, 2018). "Furthermore, the tumor xenograft experiment confirmed that UCA1 amplification could promote tumor growth in vivo." (PMID 28624787, 2017). "However, in the present study, we first confirmed the function of p21 in GBC cell proliferation in vitro and the rescue experiments showed that UCA1-mediated tumor promoting effects on GBC cell was partly dependent on the epigenetic silencing of p21 expression." (PMID 28624787, 2017). "Therefore, UCA1 may serve as an effective biomarker to predict prognosis and tumor progression of patients with cancer." (PMID 28423704, 2017). "Moreover, depletion of UCA1 further aggravated CDDP‐mediated repression on tumor growth." (PMID 29125238, 2017). "Conceivably, increased detection of UCA1 in urinary sediments might reflect only partly increased expression in cancer tissues, but instead increased shedding of urothelial cells into urine in tumour patients." (PMID 28430799, 2017). "STMN1, a microtubule-regulating protein highly expressed in tumors, promotes tumor cell proliferation, invasion, and MDR; silencing UCA1 reduces STMN1 expression." (PMID 40191723, 2025). "While several studies have identified roles of HOTAIR, UCA1, and MALAT1 in tumor progression, the transcriptional control of these lncRNAs by BCSC-associated factors remains only partially elucidated." (PMID 40781106, 2025). "Further, compared to adjacent non‐tumor tissue, patient tumor samples with LSCC, OSCC, ESCC, and hypopharyngeal squamous cell carcinoma display higher expression of UCA1." (PMID 40231344, 2025). "The pretreatment tumor tissue lncRNAs OIP5, CCAT1, UCA1, and MALAT1 were overexpressed (value more than 1) in 69.29%, 70.73%, 31.70%, and 36.58% samples, respectively, as compared to the control value (value =1) derived from normal mucosal samples of patients." (PMID 40568293, 2025). "All these results were evident in vivo as well, while the analyzed tumor specimens exhibited an increase of PTP1B expression and its positive correlation with UCA1." (PMID 38534790, 2024). "Through direct interactions with known tumor suppressing miRNAs (MALAT1, HOTAIRM1), miRNA sponging (NEAT1, UCA1), and competition with miRNAs for mRNA binding (UCA1), lncRNAs drive oncogenesis in ATC via these dynamic interactions." (PMID 38785786, 2024). "Through CREB1-mediated PI3K/Akt/mTOR signaling, UCA1 upregulates the expression of CREB1, competitively binds miR-582, and accelerates EMT pathway, thereby boosting tumor metastasis." (PMID 39119480, 2024).
tumor (continued). "HIF-1α interlocks with the responded elements in the UCA1 promoter region, inducing UCA1 expression and downregulating PTEN, activating the Akt pathway, and inducing tumor cell growth." (PMID 39119480, 2024). "Five oncogenic (LUCAT1, MIR31HG, UCA1, HIF1A-AS2, and SUMO1P3) and tumor-suppressive (LINC00312) lncRNAs were independently validated, and three key molecules were further examined." (PMID 36980216, 2023). "In this study, we found that six prognostic chemokine-related lncRNAs were expressed at different levels in tumor tissues and paired adjacent normal tissues, including LINC00675, PRG1, ROR1-AS1, ANKRD10-IT1, UCA1, and EWSAT1." (PMID 37081402, 2023). "Up-regulated tumor-promoting lncRNAs such as MALAT1, UCA1, H19, HIF1A-AS2 and down-regulated tumor suppressor lncRNAs such as NBAT1, GASS, RNCR3, etc., all of which play an important role in the formation and malignant progression of gliomas." (PMID 37153654, 2023). "For example, hypoxic tumor-derived exosomal long non-coding RNA UCA1 promotes pancreatic cancer angiogenesis, which in turn leads to its metastasis Non-coding RNA MFI2-AS1 is highly expressed in various tumor cells." (PMID 36934264, 2023). "lncRNA XIST, lncRNA UCA1, and lncRNA AX747207 can also be selectively loaded into exosomes of tumor cells and participate in tumor drug resistance." (PMID 36839784, 2023). "In conclusion, our results indicated that OSCC-CSC-sEV transfer of UCA1 promotes M2 macrophage polarization via a LAMC2-mediated PI3K/AKT axis, thus facilitating tumor progression and immunosuppression." (PMID 36483681, 2022). "Hypoxic bladder cancer cell-derived exosomal lncRNA UCA1 enhances CSCs proliferation and induces EMT to facilitate tumor metastasis." (PMID 35663957, 2022). "Several oncogenic lncRNAs, such as UCA1, NEAT1, TMPO-AS1 and OIP5-AS1, as well as some tumor suppressive lncRNAs, have been shown to participate in the chemoresistance of cancer cells." (PMID 36499136, 2022). "Given that better stability is an essential prerequisite for tumor biomarkers, we sought to assess the stability of LINC00265, LINC00467, UCA1, and SNHG1 in the isolated plasma exosomes." (PMID 36276083, 2022). "Our bioinformatics data illustrated that lncRNAs PART1, UCA1, DIRC3, HOTAIR, and HOXA11AS have more differential expression in the tumor tissues versus normal counterpart margins." (PMID 35949302, 2022). "Secondly, significant correlations were found between tumor stage and two lncRNAs (MKLN1-AS and UCA1), which tentatively revealed the relationship between lncRNAs and the degree of the disease." (PMID 36119544, 2022). "In this study, we revealed that OSCC-CSC-sEVs transferring the lncRNA UCA1 promote M2 macrophage polarization via a LAMC2-mediated PI3K/AKT axis, thereby facilitating tumor progression and immunosuppression." (PMID 36483681, 2022). "UCA1 also binds to miR-204 to inhibit the degradation of SOX4, thereby promoting the invasion and metastasis of tumor cells." (PMID 35241975, 2022). "Given that better stability is an essential requirement for tumor biomarkers, the stability testing of LINC00265, LINC00467, UCA1, and SNHG1 in the isolated plasma exosomes was performed." (PMID 36276083, 2022). "In TNBC, multiple lncRNAs had been identified to regulate EMT pathways and tumor invasion via interacting with various molecules, such as LINC01638, GAS5, UCA1, ARNILA, and NNT-AS1." (PMID 34873403, 2021). "We found that seven lncRNAs were highly expressed in tumor patients in the GTEx-TCGA database, and LncRNA CASC19/UCA1/LINC01094/LINC02323 were confirmed in both pancreatic cell lines and FISH relative quantity." (PMID 35047414, 2021). "LncRNA of UCA1 functions as an oncogene in NSCLC, acting mechanistically by upregulating ERBB4 in part through the sponging of tumor suppressor miR-193a-3p." (PMID 33628829, 2021).
tumor (continued). "Using the human granulosa-like tumor cell line (KGN) and PCOS mice model, we explored the function of lncRNA UCA1 in the pathological progression of PCOS." (PMID 33743811, 2021). "They specifically found that exosomal lncRNA UCA1 could act as a growth inhibitor in EC as its overexpression inhibited cell proliferation, migration, invasion, and colony formation significantly, as well as tumor growth in vivo via direct targeting of high levels of miR-613." (PMID 33936199, 2021). "Previous studies have indicated that up-regulation of lncRNA UCA1, TTN-AS1 and FEZF1-AS1 in LUAD were related to poor prognosis, and down-regulation of LCAL62 also promoted tumor progression and invasion." (PMID 33968781, 2021). "Researchers uncovered that the expressions of LncRNAs, UCA1, CASC9, and FAL1 promote tumor progression in OSCC." (PMID 34912458, 2021). "Apart from the interaction with miR-135a, lncRNA UCA1 also inhibited miR-96, a tumor suppressor mRNA, resulting in the upregulation of forkhead box O-3 (FOXO3) to promote tumor progression." (PMID 33936199, 2021). "Among lncRNA, HEIH and UCA1 develop their oncogenic functions by inhibiting their target miRNAs and consequently reversing the inhibition of NOS and promoting tumor proliferation." (PMID 34200849, 2021). "In this sense, HEIH and UCA1 develop their oncogenic functions by inhibiting their target miRNAs, and consequently reversing the inhibition of NOS and promoting tumor proliferation." (PMID 34200849, 2021). "The results illustrated that the high expression of UCA1 positively correlated with serum AFP (χ2 = 3.921, p < 0.05), tumor size (χ2 = 5.591, p < 0.05) and distant metastasis (χ2 = 5.345, p < 0.05)." (PMID 33565716, 2021). "We found that in the tumor tissues as well, CHRF levels were the most up-regulated, compared to UCA1 and PANDAR." (PMID 32901049, 2020). "Lnc UCA1, along with the enzyme hexokinase-2 (HK2), has been found to enhance glycolysis in radioresistant tumor cells, thus participating in the regulation of radiotherapy sensitivity." (PMID 32122355, 2020). "LncRNA-UCA1 and SNHG1 were significantly up-regulated in NSCLC tissues than in paired adjacent healthy tissues, and the up-regulation of UCA1 and SNHG1 promotes tumor progression." (PMID 32975291, 2020). "Remarkably, silencing SIK2 improved PTX sensitivity and inhibited tumor growth, and this action was abolished by miR-654-5p inhibition, suggesting that SIK2 is a downstream target of UCA1/miR-654-5p." (PMID 32854207, 2020). "HA/CD44-activated lncRNA UCA1 also downregulates miR-145 expression and stimulates ROCK expression required for cytoskeletal activation and tumor cell motility (e.g., migration and invasion)." (PMID 31293964, 2019). "Meanwhile, lncRNAs UCA1, RP11-458F8.4, RP1-239B22.5, and ALMS1-IT1, which were markedly upregulated in tumor tissues, have higher expression levels in late-stage cancer." (PMID 30984308, 2019). "To verify that UCA1 regulate EZH2 and CDK6 expression through sponging miR-26a and miR-26b, we first quantified the EZH2 and CDK6 protein level in tumour and control tissues by immunoblotting." (PMID 31272462, 2019). "Treatment of cells with lncRNA UCA1 RNAi inhibitor or miR-145 mimic or a ROCK inhibitor, Y-27632 significantly reduces tumor cell invasion." (PMID 31293964, 2019). "The results of these studies strongly indicate that lncRNA LncRNA UCA1 is one of the important regulatory molecules in controlling miR-145-ROCK pathway and tumor cell migration and invasion." (PMID 31293964, 2019). "A research clarified that the level of UCA1 in CRC tissues is positively correlated with CRC tumor size and advanced tumor stages." (PMID 31480503, 2019). "We compared the expression levels of nine hypoxia-related lncRNAs39, 40, 41 (H19, HOTAIR, NEAT1, linc-ROR, UCA1, WT1, HINCUT1, LINK-A, LincRNA-p21) between tumor central and peripheral cells." (PMID 29106390, 2018).